FERMT2 (FERM domain containing kindlin 2)
Diseases named in the same sentence as FERMT2 in open-access papers (continued):
Sharing a sentence is not in itself a finding about the gene and the disease.
lymphoma (1 paper, 2022). A malignant (clonal) proliferation of B- lymphocytes or T- lymphocytes which involves the lymph nodes, bone marrow and/or extranodal sites. "Our random forest biomarker discovery pinpointed three novel biomarker genes not previously associated with BCNHL, YES1, FERMT2, and FAM98B, which show high fidelity in predicting lymphoma presence based on transcriptional levels in B-cells." (PMID 36873459, 2022).
preeclampsia (1 paper, 2024). Preeclampsia is a hypertensive disorder of pregnancy that is characterized by new-onset hypertension with proteinuria presenting after 20 weeks of gestation, and depending on mild or severe forms may initially present with severe headache, visual disturbances, and hyperreflexia. "These predicted targets included classical decidualization-inducing genes as well as genes previously reported to have preeclampsia-related transcriptional changes in trophoblasts, such as FERMT2 and RORB." (PMID 39090334, 2024). "These include decidualization markers such as PRLR and IGFBP3, as well as genes that have previously been reported to have roles in trophoblast invasion, such as FERMT2 and RORB, for which expression changes in preeclampsia have been observed in fetal placenta." (PMID 39090334, 2024).
renal carcinoma (1 paper, 2024). A carcinoma arising from the epithelium of the renal parenchyma or the renal pelvis. "A stage-specific decrease in FERMT2 mRNA expression was not pronounced except in renal cancer, LUAD, or BRCA." (PMID 38548811, 2024).
Sepsis (1 paper, 2025). Sepsis is defined as life-threatening organ dysfunction caused by a dysregulated host response to infection. "In line with Ilk1 and Fermt2, genes encoding for the integrin subunits (Itga7 and ItgB1) were upregulated (more than 2-fold; P < 0.001 versus healthy control mice) after five days of sepsis." (PMID 41385533, 2025). "In TA, the observed upregulation of Ilk1 and Fermt2 in TA was successfully prevented in mice treated with rAAV-delivered shRNAs specifically targeting Ilk1 or Fermt2 mRNA over the 5 days of sepsis." (PMID 41385533, 2025). "This argues against a key role for Ilk1 or Fermt2 in the development of sepsis-induced muscle wasting." (PMID 41385533, 2025). "After five days of sepsis, both Ilk1 and Fermt2 mRNA levels were elevated in septic control mice compared to healthy control mice." (PMID 41385533, 2025). "Two weeks prior to sepsis induction, the tibialis anterior muscles (TA) of the mice were injected with adeno-associated viral vectors (AAV) encoding short-hairpin RNA (shRNA) specifically targeting Ilk1 or Fermt2 mRNA." (PMID 41385533, 2025). "Sepsis induced upregulation of integrin-receptor-complex-related genes but attenuating the upregulation of Ilk1 or Fermt2 did not affect the development of muscle weakness, although muscle fiber size was better preserved, arguing against a key role for Ilk1 or Fermt2." (PMID 41385533, 2025). "In rAAV-sh-controls, sepsis induced upregulation across TA and EDL muscle of Ilk1 and Fermt2 and integrin-receptor-complex-related genes Itga7, ItgB1, Tln1, Lims1, Lims2, Parva (P < 0.001), whereas in SOL muscle Lims1, Lims2 and Fermt2 were not and Vcl1 (P < 0.001) was upregulated." (PMID 41385533, 2025). "In SOL muscle, gene expression of Ilk1 was upregulated compared to healthy control mice (P < 0.001), whereas the expression of Fermt2 was not affected by sepsis (P = 0.6)." (PMID 41385533, 2025). "In the sepsis experiment, when sepsis was induced by cecal ligation and puncture (2 weeks post rAAV injection), muscle tissue was not yet accessible for gene or protein assessment of Ilk1/ILK1 and Fermt2/KIND2." (PMID 41385533, 2025). "Specific rAAV-shRNA treatment in the TA muscle two weeks prior to sepsis induction, attenuated the upregulation of Ilk1 and Fermt2 mRNA, but did not affect muscle wasting, weakness or downstream signaling pathways." (PMID 41385533, 2025). "Our data shows an upregulation of Fermt2 gene expression after five days of sepsis in TA and EDL, but not in SOL." (PMID 41385533, 2025).
systemic lupus erythematosus (1 paper, 2022). An autoimmune multi-organ disease typically associated with vasculopathy and autoantibody production. "The analysis of KEGG pathway indicated the genes co-expressed with FERMT2 are primarily involved in the natural killer cell mediated cytotoxicity, systemic lupus erythematosus and other pathways." (PMID 36480537, 2022).
tauopathy (1 paper, 2021). Neurodegenerative disorders involving deposition of abnormal tau protein isoforms (tau proteins) in neurons and glial cells in the brain. "The role of FERMT2 in AD and tauopathy is largely unknown, but a genome-wide siRNA screen suggested that FERMT2 may increase Aβ peptide production by elevating the levels of mature APP at the cell surface via membrane recycling." (PMID 34575087, 2021).
tumor (57 papers, 2008 to 2025). "In GC, FERMT2 upregulation has been linked to increased invasive potential via tumor-associated macrophages and has been implicated in lymphatic metastasis." (PMID 40024947, 2025). "Transforming growth factor beta 2 (TGFβ2) secreted by tumor-associated macrophages (TAMs) promotes GC cell invasion by promoting the level of FERMT2." (PMID 38352691, 2024). "Fermt2 and Tiam1 are implicated in cellular migration and invasion, suggesting that disruption of ephrinB2 signaling impairs mechanisms that facilitate tumor cell penetration of vessel walls." (PMID 39489818, 2025). "Collectively, these results demonstrate that knockdown of fibroblast-derived TNS1 and FERMT2 impedes CRC tumour growth." (PMID 41405822, 2025). "The proportions of distinct cell subpopulations were different between primary tumors and peritoneal metastases, with FERMT2 RNA levels higher in peritoneal metastasis cells than in primary tumor cells." (PMID 40024947, 2025). "Based on our findings, we conclude that myofibroblast-derived CRC, TNS1, and FERMT2 orchestrate tumour progression by upregulating FN1, which subsequently activates integrin and FAK signaling in cancer cells." (PMID 41405822, 2025). "This provided valuable insights into the specific cellular contexts of FERMT2 expression, indicating its potential roles in tumor-stroma interactions and the TME." (PMID 38910148, 2024). "Fermitin family homolog 2 (FERMT2) was reported to promote tumor cell adhesion, migration, and invasion in BCCs to induce EMT." (PMID 37511111, 2023). "The genomic alterations, mutations and target proteins of FERMT2 during development of CRC, as well as its roles in tumor immunization were predicted by bioinformatics analysis." (PMID 36480537, 2022). "It has been suggested that FERMT2 acts either as a tumor promoter or suppressor in different cancers." (PMID 33934696, 2021). "Notably, the spatial redistribution of FERMT2-positive myofibroblasts from the basal lamina in normal tissue to desmoplastic regions in tumours suggests tumour microenvironment–driven reprogramming of stromal signaling niches." (PMID 41405822, 2025). "Functionally, knockdown of Tensin 1 or FERMT2 in fibroblasts attenuated tumour growth in vivo." (PMID 41405822, 2025). "Conversely, FERMT2 exhibited a significant downregulation in HNSCC tumor tissues." (PMID 37989855, 2023). "It is reported that FERMT2 participated in the cancer progression and metastasis through regulating numerous signaling pathways, which are essential for survival, proliferation, migration and invasion of tumor cells." (PMID 36480537, 2022). "Additionally, higher FERMT2 expression was strongly associated with long-term OS and FP in NSCLC, and FERMT2 was correlated with tumor grade and nodal metastasis." (PMID 33934696, 2021). "More importantly, FERMT2 was found to be significantly underexpressed in tumor tissues, and COPG1 was slightly overexpressed in tumor tissues; thus, it was expected that FERMT2 was a positive predictor for overall survival and that COPG1 was a risk factor for disease-free survival." (PMID 33850477, 2021). "It is hypothesized that FERMT2 may have effects on tumor immunity through interactions with integrin-like protein." (PMID 33648465, 2021). "Additionally, FERMT2 expression showed a similar relationship with tumor purity and the infiltration of CD8+ T cell, CD4+ T cell, Macrophage, Neutrophil, and Dendritic cell in LUAD and LUSC." (PMID 33934696, 2021). "In addition to data at the transcriptional level, IHC staining confirmed a decrease in protein levels of CD163 and CD206 (representing tumor-infiltrating M2 macrophages) with increased level of FERMT2 proteins (CD163, R = 0.543, P < 0.001; CD206, R = 0.500, P = 0.001)." (PMID 38352691, 2024). "CPLF primarily reflects extracellular matrix deposition in the tumour microenvironment, with Tensin 1 (TNS1) and Fermitin family homologue 2 (FERMT2) as the highest-weighted features." (PMID 41405822, 2025).
tumor (continued). "We found 5 potential target genes (SKP2, SMO, SDCBP, FERMT2 and PGAM1) that were consistently predicted by the three softwares and involved in tumor-related signaling pathway." (PMID 34221971, 2021). "In the univariable Cox analysis, clinical tumor stage, age, and the expression levels of NFE2L2, ITGAV, GET4, FERMT2, CRB3, CDH2, and BCL2L1 were prognostic factors for OS." (PMID 33850477, 2021). "The expression of CDH2, MDM2 and TNFSF10 was significantly upregulated in tumor tissue, while expression of PAX8 and FERMT2 was significantly downregulated." (PMID 33850477, 2021). "EMT signal in tumor cells is at least partially driven by fibroblasts, and there is a large overlap in the gene expression profiles of mesenchymal signal and EMT, so we here further investigated the significance of FERMT2 in control of EMT." (PMID 38352691, 2024). "The expression levels of FERMT1 and FERMT2 were remarkably distinct in different tumor stages of LUAD and LUSC, while there was no significance between FERMT3 and different tumor stages." (PMID 33934696, 2021).
cancer (53 papers, 2010 to 2025). A tumor composed of atypical neoplastic, often pleomorphic cells that invade other tissues. "Kindlin-2 (FERMT2) is associated with the pathogenesis of several cancers." (PMID 35158908, 2022). "To investigate how TNS1 and FERMT2 expression in myofibroblast promotes cancer progression, we quantified the activities of 284 signaling pathways in CPTAC-2 proteomic data." (PMID 41405822, 2025). "IHC showed representative staining of cancer and normal tissues and showed that FERMT2 was expressed in the nucleus and cytoplasm." (PMID 38352691, 2024). "Notably, the expression levels of FERMT2 in cancer tissue can be categorized into three distinct patterns." (PMID 38910148, 2024). "FERMT2 has been shown to modulate β1 integrins activity in cancers." (PMID 36480537, 2022). "However, FERMT2 is upregulated in many kinds of cancers and modulates cancer progression through various molecular pathway." (PMID 36480537, 2022). "YES proto-oncogene 1, Src family tyrosine kinase (YES1), FERM domain containing kindlin 2 (FERMT2), and family with sequence similarity 98 member B (FAM98B) have previous associations with cancers, but our finding that they are associated with BCNHL as high-potential biomarkers is novel." (PMID 36873459, 2022). "The potential role of FERMT2 in various types of cancer has been extensively explored." (PMID 33934696, 2021). "Supporting this, our RNAseq data show decreased expression of pro-migratory and pro-invasive genes, such as Fermt2 and Tiam1, in ephrinB2 knockout MOC2 cancer cells." (PMID 39489818, 2025). "Among these genes, seven proteins (MAP2K1, FERMT2, HMGB2, FAF2, STK26, THRAP3, and KRT15) showed significant differences between carcinoma and adjacent tissues (TCGA-HNSC database)." (PMID 39319867, 2025). "FERMT2 readily binds ITGB1 cytoplasmic domains and has also been reported to be highly expressed within cancers where it promotes migration and invasion." (PMID 30382829, 2018). "Overall, we established a fibroblast-FERMT2-EMT-M2 macrophage axis, which may play a key role in the mesenchymal phenotype of GC and serve as a promising target for advanced cancer therapy." (PMID 38352691, 2024). "According to the regulation efficacy data, the positive regulation of TRIM15 and NHERF1 by CREB1 was reversed from normal to cancer; the negative regulations of TCEAL2, RBPMS2 and FAM20C by CREB1 disappeared; and the negative regulation of FERMT2 was reversed from normal to cancer." (PMID 35421923, 2022). "Therefore, our study is the first to identify the role of the TGF-β1/FERMT2/TβRI positive feedback loop specifically in the context of anoikis resistance, rather than merely its involvement in promoting cancer cell proliferation and migration." (PMID 40024947, 2025).
FERMT2 also shares sentences with these, for which no sentence is quoted: bladder cancer (6 papers); glioma (6); pancreatic ductal adenocarcinoma (6); diabetes (3); liver fibrosis (3); lymph node metastasis (3); non-small cell lung carcinoma (3); triple-negative breast carcinoma (3); breast invasive carcinoma (2); breast tumor (2); cardiomyopathy (2); cardiovascular disease (2); colon adenocarcinoma (2); Glucose intolerance (2); Hypertension (2); liver diseases (2); male infertility (2); Obesity (2); Osteopenia (2); osteoporosis (2); ovarian carcinoma (2); renal fibrosis (2); abdominal aortic aneurysm (1); actinic keratosis (1); acute liver failure (1); acute lung injury (1); adenocarcinoma of the (1); Aortic dissection (1); bladder urothelial carcinomas (1); cardiac hypertrophy (1).
A further 51 diseases each share a sentence with FERMT2 in 1 paper.